CCN1 (cellular communication network factor 1)
Diseases named in the same sentence as CCN1 in open-access papers (continued):
Sharing a sentence is not in itself a finding about the gene and the disease.
tumor (282 papers, 2007 to 2026). "We next analyzed tumor cell death during coculture with macrophages and found that Ccn1‐deficient cells exhibited increased susceptibility to macrophage‐induced cell death." (PMID 40287974, 2025). "The proportion of M1 macrophages cocultured with Ccn1‐deficient tumor cells was significantly higher." (PMID 40287974, 2025). "CCN1 mRNA levels were significantly higher in PDAC tumor tissues than in normal pancreatic tissues, and high CCN1 expression was associated with shorter overall survival in patients." (PMID 40287974, 2025). "To confirm the inhibition of tumor growth associated with decreased chemokine expression in Ccn1‐KO tumor, we focused on CXC chemokines, including CXCL1, CXCL3, and CXCL5, which bind to CXCR2, as well as CCL2 and CCL7, which bind to CCR2." (PMID 40287974, 2025). "CCN1-deficient stroma impaired tumor-associated collagen production (69.76% ± 2.44% vs. 47.65% ± 8.21%, CCN1f/f vs. CCN1−/−)." (PMID 38363129, 2024). "Loss of Ccn1 expression by fibroblasts significantly impaired metastasis of tumor cells to lung and increased recruitment of CD4+ T cells into tumors." (PMID 38363129, 2024). "The anti-tumour effect of VB was associated with the activation of M1 polarization regulated by the CCN1-mediated AKT/NF-κB pathway." (PMID 35785168, 2022). "In tissues, CCN1 was expressed in the cytoplasm of tumour cells, with strongly stained cells associated with blood vessels." (PMID 35052688, 2021). "In salivary adenoid cystic carcinoma tissues, CCN1 expression is positively correlated with the histopathological features of the tumours and is associated with advanced disease stages, metastasis in distant organs and overall poor prognosis." (PMID 34205668, 2021). "CCN1 proteins are found to be associated with tumor cell proliferation as well as migration and adhesion of tumor cells." (PMID 34940056, 2021). "CCN1 is aberrantly expressed in many cancer types and high levels associate with tumor aggressiveness and metastasis." (PMID 28694244, 2017). "Quantification of collagen I and III fibers in tumor regions with high (peri‐necrotic areas) or low Ccn1 expression by Sirius red staining showed that higher collagen content associated with high Ccn1 expressing regions." (PMID 28694244, 2017). "CCN1 is a cysteine-rich intercellular matrix protein, high expression of CCN1 is associated with the progression and poor prognosis of multiple cancers and is involved in tumor growth, angiogenesis, and cancer cell adhesion, migration, and invasion." (PMID 40695891, 2025). "To verify whether Ccn1‐deficient KPC cells enhance tumor sensitivity to anti‐PD1 therapy, we subcutaneously injected KPC cells with or without Ccn1 into immunocompetent mice." (PMID 40287974, 2025). "Our study found seven downstream factors that may be associated with chemoresistance, LTF, SOD2, STAT1, CDKN2A, CD81, RAC1, and NDRG1 and five factors that may be associated with tumor development, CCN1, DCTN3, MUC1, H1-5, and SLC1A5." (PMID 35421932, 2022). "In addition, in immunodeficient mice implanted with human gastric, naturally CCN1 deficient, adenocarcinoma cells induced expression of the CCN1 cDNA is an effective promoter of angiogenesis, concomitant with tumour vascularisation and growth." (PMID 35052688, 2021). "Hence, an association between CCN1 and stiffness can be found in vivo and we investigated further the role of CCN1 in endothelial cells in the tumor context." (PMID 28694244, 2017). "CCN1 stimulates tumor growth and is associated with an increased intra-tumor vascularization." (PMID 27809279, 2016). "Furthermore, changes in the transcriptional expression of C-Man-Trp metabolism-related genes, C-mannosyltransferases (Dpy19l1 and Dpy19l3), and thrombospondin type I repeat superfamily genes (Thbs1, Spon1, and cellular communication network factor 1) were noted in tumor-associated cells and tissues." (PMID 41812877, 2026).
tumor (continued). "Notably, Ccn1‐KO significantly inhibited tumor growth in immunocompetent mice, while no significant weight loss was observed throughout the study, indicating that antitumor immunity contributed to the effects Ccn1 deficiency." (PMID 40287974, 2025). "Additionally, Ccn1‐deficient tumor cells exhibit sensitivity to TNFα." (PMID 40287974, 2025). "However, whether macrophage polarization regulated by the CCN1-mediated AKT/NF-κB signalling pathway is associated with the anti-tumour effect of VB remains illusively." (PMID 35785168, 2022). "Functionally, CCN1 plays a critical role in promoting cell proliferation, tumor growth, and invasion across various malignancies." (PMID 40287974, 2025). "Specifically, it demonstrates that a reduction in CCN1 expression within soft matrices can attenuate the migratory and proliferative capabilities of tumor cells." (PMID 40416783, 2025). "In vivo experiments confirm that VB reduces tumor volume and weight, inhibits cell proliferation, and promotes apoptosis in OC tissues, with CCN1 overexpression diminishing VB’s effects." (PMID 40330466, 2025). "Chemoattractants released by OV-infected tumor cells, such as CCL-2 and CCN1, attract TAMs and other immune cells to the tumor site." (PMID 40061139, 2025). "CCN1 exhibits both pro-tumorigenic and tumor-suppressive activities depending on the primary site of malignancy and context within the local microenvironment." (PMID 41012700, 2025). "Deletion of CCN1 not only suppresses tumor growth but also enhances immune cell infiltration and increases tumor sensitivity to both chemotherapy and immunotherapy." (PMID 40287974, 2025). "Combining Ccn1 depletion with gemcitabine treatment leads to higher tumor inhibition compared to gemcitabine alone." (PMID 40287974, 2025). "CCN1 expression status can be used to discriminate between malignant verses benign tumor lesions, making it a promising biomarker to use in conjunction with existing diagnostic tools to establish improved patient treatment plans." (PMID 41012700, 2025). "CCN1/CYR61 binds to the integrin αvβ3 receptor, stimulate tumor growth, chemoresistance, and angiogenesis." (PMID 41294885, 2025). "Targeting CCN1 resulted in inhibition of tumor cell proliferation and angiogenesis, and restoration of sensitivity to alectinib in reversible drug-resistant cells." (PMID 40234387, 2025). "Previous studies have reported that CCN1 and CCN2 are associated with tumor growth, migration, and drug resistance." (PMID 40234387, 2025). "Verbascoside (VB), a phenylpropanoid glycoside, demonstrates significant anti-tumor activity against ovarian cancer (OC) by facilitating M1 macrophage polarization through the CCN1-AKT/NF-κB signaling pathway." (PMID 40330466, 2025). "CCN1 knockdown in MES‐GSCs reduced the tumor stemness, invasion, and tumorigenicity, whereas CCN1 overexpression in PN‐GSCs exhibited the opposite effects in vivo and in vitro." (PMID 39659236, 2024). "If fibroblast-specific expression of CCN1 is required for ECM elaboration in tumor stroma remains uninvestigated." (PMID 38363129, 2024). "A range of primary GBM and GSC cell models were then used to demonstrate the regulatory role of CCN1 via the phenotype validation, tumor sphere formation assays, extreme limiting dilution assays (ELDA), and transwell assays." (PMID 39659236, 2024). "For instance, CCN1 can enhance cell survival and induce apoptosis, promote cell proliferation and trigger cell-cycle arrest, and support tumor growth while also suppressing tumorigenesis in different contexts." (PMID 39273316, 2024). "In conclusion, our study suggests that the signaling of TGF-β1 and LPA between mPSCs and Panc1 cells shifts mPSCs to a more myCAF-like (tumor-suppressive) phenotype and increases the expression of CCN1 in Panc1 cells." (PMID 39273316, 2024).
tumor (continued). "The concentrations of the growth factors and cytokines TGF-ß1 and VEGF, as well as the tumor-related proteins CCN1 and CCN3, were evaluated in cell culture supernatants of MG63 and HT1080 in response to indirect PRF treatment for 2 days." (PMID 38671725, 2024). "We found that mice harboring a fibroblast-specific deletion of Ccn1 displayed significantly impaired metastasis of tumor cells to the lung (0.967% ± 0.297% vs. 0.247% ± 0.070%, CCN1f/f vs. CCN1−/−)." (PMID 38363129, 2024). "Both in vitro and in vivo assays indicated that knockdown of CCN1 in MES‐GSCs reduced the tumor stemness, proliferation, invasion, and tumorigenicity, whereas CCN1 overexpression in PN‐GSCs exhibited the opposite effects." (PMID 39659236, 2024). "Compared with the control mice, CCN1‐silencing mice exhibited decreased tumor burdens on Day 30 and prolonged survival periods." (PMID 39659236, 2024). "Matrix stiffness in tumor model systems can induce endothelial CCN1 secretion and was postulated as an autocrine factor in the endothelium and functioning in a paracrine fashion as a tumor cell adhesion ligand for gaining access to the circulation." (PMID 35300411, 2022). "In vivo experiments verified that VB inhibited tumour growth and promoted M1 polarization, which is regulated by the CCN1-mediated AKT/NF-κB pathway." (PMID 35785168, 2022). "Previous studies on CCN1 mainly focused on tumor, tissue damage repair, cardiovascular development and so on." (PMID 35547732, 2022). "In the present study, we focused on the significant correlation between DGC and macrophage signature genes, and established that DGCs secrete CCN1 to promote macrophage infiltration into the GBM tumor microenvironment." (PMID 33618763, 2021). "In general, cytoplasmic, and membranous CCN1 staining was visible in tumour cells, with strong staining in elongated cells and cells in close proximity to blood vessels (data not shown), suggesting a correlation between CCN1 and invasive cell migration." (PMID 35052688, 2021). "Several previous studies reported that CCN1 participates in cancer development and can serve as both a tumor suppressor and promoter." (PMID 33833779, 2021). "Next, to determine the CCN1 distribution and its correlation with macrophage infiltration into GBMs, frozen sections of tumor tissue from a mouse de novo GBM model were coimmunostained with CCN1 and M2 macrophage marker CD206." (PMID 33618763, 2021). "U343 cells overexpressing CCN1 migrated more readily and produced larger, more vascularised tumours in nude mice." (PMID 35052688, 2021). "Ectopic expression of CCN1 can stimulate the dissemination of cancer cells from the primary tumor site, and can facilitate their binding to other tissues by modulating integrin proteins." (PMID 34940056, 2021). "Collectively, these results demonstrate that DGCs contribute to GSC-dependent tumor progression by shaping a mesenchymal microenvironment via CCN1-mediated macrophage infiltration." (PMID 33618763, 2021). "CCN1-high GBMs exhibited higher stromal and immune signatures and lower tumor purity than CCN1-low GBMs." (PMID 33618763, 2021). "Collectively, these results suggest that DGCs augment macrophage infiltration into tumors and tumor progression, at least in part, through secretion of CCN1." (PMID 33618763, 2021). "In tumour progression, CCN1 has been shown to promote invasion, angiogenesis, cell proliferation, cell survival and metastasis." (PMID 35052688, 2021). "DGCs promoted macrophage migration in vitro and macrophage infiltration into tumor tissue in vivo through secretion of CCN1." (PMID 33618763, 2021). "Contradicting results, however, have been reported regarding cell type (plasma cells versus stromal cells) expressing CCN1 and its effect on tumor cell growth." (PMID 33428075, 2021). "Previous, mostly in vitro, studies showed that CCN1 serves as a tumor promoter in most cancers but can also acts as a tumor suppressor in some cancers." (PMID 33833779, 2021).
tumor (continued). "We found that tumor areas with more CD206-positive macrophage infiltration showed more CCN1 staining." (PMID 33618763, 2021). "An in vivo study also showed the inhibition of tumor growth and metastasis following anti-CCN1 treatment." (PMID 33105556, 2020). "The mice intratibially injected with the CCN1 overexpressing SAOS-2 cell showed more aggressive tumor growth and lung metastases accompanied by a short survival period." (PMID 33105556, 2020). "The paradoxical effect of the CCN1 protein has been reported by many researchers, in which it can serve as both tumor suppressor and oncogene." (PMID 33105556, 2020). "Secretion of CCN1 by tumours can facilitate tumour angiogenesis, and knockdown of ccn1 in zebrafish resulted in defective vessels in terms of migration and development, especially sprouting behaviour." (PMID 31429823, 2019). "Integrin αvβ3 inhibitor repressed tip cell number and sprouting in postnatal retinas from endothelial cell-specific Ccn1 transgenic mice, and allograft tumours in Ccn1 transgenic mice showed hyperactive vascular sprouting." (PMID 31429823, 2019). "Stiffness plays a key role in regulating the matricellular protein CCN1/CYR61 in endothelial cells during tumor metastasis, suggesting that target stiffness‐induced changes is a potential mechanism to impair tumor metastasis." (PMID 30745454, 2019). "In endothelial cells, stiffness promotes tumor metastasis via activating the CCN1/CYR61/β-catenin/N-cadherin cascade and enhancing the binding affinity of the tumor cells to the endothelium." (PMID 30934860, 2019). "Ccn1 overexpression in ECs resulted in significant upregulation of VEGFR2 expression as well as increased sprouting activity in the central region of the tumour." (PMID 31429823, 2019). "(A) LLC allograft tumour tissues in WT and Ccn1-EC-specific TG mice were extracted at 10 days after inoculation, sectioned, and immunostained with anti-CD31 and anti-PDGFβ antibodies and green and red fluorescently labelled secondary antibodies." (PMID 31429823, 2019). "The desmoplastic reaction that accompanies tumor aggressiveness induces increased levels of endothelial CCN1, which, in turn, upregulates the N-Cadherin available at the surface of the blood vessels." (PMID 29209654, 2017). "We build on this by characterizing a molecular mechanism within ECs, whereby the tumor‐induced matrix stiffness increases CCN1 levels, which can modulate β‐catenin signaling and consequently N‐cadherin levels." (PMID 28694244, 2017). "We envisioned that in a tumor context, the CCN1‐regulated N‐cadherin levels control the heterotypic interaction between cancer cells and the endothelium to aid the promotion of intravasation and metastasis." (PMID 28694244, 2017). "Here we discovered that tumor stiffness alters the CCN1/β‐catenin/N‐cadherin pathway that contributes to the metastatic cascade by facilitating the binding of the cancer cells to the blood vessels." (PMID 28694244, 2017). "High Ccn1 expression was found only in some regions of the tumor which were adjacent to the necrotic areas." (PMID 28694244, 2017). "Knockdown of CCN1 using antibodies or siRNA suppressed proliferation and increased apoptosis suggesting that CCN1 was acting as a tumour promoter in AML." (PMID 27485291, 2016). "Clinical studies suggest that the expression of CCN1 correlates with tumor stage, size, lymph node involvement, and represents a poor prognostic factor in various cancers, including prostate." (PMID 25926554, 2015). "CCN1 is a potent proangiogenic molecule, and a previously published study suggested the critical role of CCN1 in the Hedgehog-influenced proangiogenic tumor microenvironment." (PMID 24551846, 2014). "Our study suggests that CCN1 regulates Bcl-xL, c-Myc, and Bax and acts as a tumor promoter through the MEK/ERK pathway." (PMID 25187756, 2014).
tumor (continued). "The data suggested that CCN1 is a tumor promoter in AML that acts through the MEK/ERK pathway to up-regulate c-Myc and Bcl-xL and to down-regulate Bax." (PMID 25187756, 2014). "In contrast, CCN1 is a tumor suppressor in non-small cell lung cancer, endometrial adenocarcinoma and melanoma." (PMID 25187756, 2014). "The importance of CCN1 in tumorigenesis originates from its diverse molecular functions which influence tumor development and metastasis by modulating angiogenesis, epithelial mesenchymal transition (EMT), and anoikis resistance." (PMID 24965524, 2014). "Our findings suggest CCN1 as a MSC-induced factor with relevance in tumor relapse and development of secondary malignancies." (PMID 24965524, 2014). "MSC-dependent splicing that governs CCN1 protein translation, as shown here, is extremely relevant in both physiologic processes like regeneration and in tumor development, e.g. by enhancing angiogenesis, especially in myeloma bone disease." (PMID 24965524, 2014). "In this current study, we showed that β-catenin elevation and translocation in ESCC tumor cells are dependent on high level of CCN1." (PMID 22701179, 2012). "This suggests that CCN1 plays a pivotal role in promoting tumor invasion in soft ECM environments." (PMID 40416783, 2025). "CCN1 has been reported to affect tumor growth through its potent angiogenic activity." (PMID 40234387, 2025). "To investigate whether Ccn1‐deficient KPC cells affect macrophage polarization, we cocultured tumor cells and M1 macrophages and measured the proportion of M1 macrophages." (PMID 40287974, 2025). "Our study found that knockdown of CCN1 could cause the downregulation of VEGFA via the AKT pathway, which could lead to the suppression of tumor growth and angiogenesis." (PMID 40234387, 2025). "This suggests that Ccn1 regulates collagens and chemokine expression to promote tumor progression." (PMID 40287974, 2025). "The upregulation of CCN1 is consistent with the enhanced proliferation and invasive potential observed in the soft matrix model, suggesting its potential role in mediating the biomechanical regulation of tumor progression in the soft model." (PMID 40416783, 2025). "CCN1/Cyr61 (cysteine‐rich angiogenic inducer 61) and CCN2/CTGF (connective tissue growth factor) have been implicated in various stages of cancer progression, including tumor initiation, angiogenesis, invasion, and metastasis." (PMID 38545253, 2024). "As fibroblast-specific deletion of Ccn1 resulted in impaired collagen organization and neovascularization, we reasoned that CCN1-deficient stroma would enhance the ability of CD4+ T cells to penetrate tumor cells." (PMID 38363129, 2024). "MORC3 deficiency downregulated the E-cadherin (CDH1) tumor suppressive gene and the keratin 14 (KRT14) epithelial differential marker but significantly upregulated the expression of oncogenic JUN, CCND1, CCND2, and CCN1 at the transcriptional level." (PMID 39329063, 2024). "Interestingly, p‐FAK/p‐MEK/p‐ERK/p‐STAT3 also significantly increased after the addition of exogenous recombinant CCN1, implicating an autocrine/paracrine regulatory mechanism of this secreted protein within the tumor microenvironment." (PMID 39659236, 2024). "Interestingly, CCN1 expression is distinctly upregulated in GBM tissues than in adjacent non‐tumor tissues." (PMID 39659236, 2024). "By using this co-culture model, we now revealed the new function of myCAFs, that is, increasing gemcitabine sensitivity of Panc1 cells, presumably through upregulation of CCN1 expression, adding another puzzle piece to the anti-tumor/protector function of PSCs." (PMID 39273316, 2024). "These cell types play critical roles in tumor progression and response to therapy, and their interaction with GSCs could significantly influence the expression and function of CCN1." (PMID 39659236, 2024).